CD300LB (CD300 molecule like family member b)
Description:
Acts as an activating immune receptor through its interaction with ITAM-bearing adapter TYROBP, and also independently by recruitment of GRB2.
Synonyms: CLM-7; IREM-3; TREM-5; CD300b; CLM7; IREM3; TREM5; CMRF35-A2
Tractability: Antibody: its Gene Ontology location is reachable by antibodies, with high confidence; UniProt places it where antibodies can reach, with medium confidence; UniProt predicts a signal peptide or a membrane-spanning region; the Human Protein Atlas places it where antibodies can reach.
Gene: Protein-coding gene on chromosome 17 (74,519,000 to 74,531,475, reverse strand). Ensembl gene ENSG00000178789.
Subcellular location: Cell membrane
Subcellular location (Human Protein Atlas): Plasma membrane
Pathways (Reactome):
Immune System: DAP12 interactions; Immunoregulatory interactions between a Lymphoid and a non-Lymphoid cell
Gene Ontology:
Molecular function: identical protein binding; protein binding; transmembrane signaling receptor activity
Biological process: immune response-activating signaling pathway
Cellular component: plasma membrane
Genetic constraint (gnomAD): Loss-of-function variants: 15 observed, 19.42 expected, observed/expected ratio (o/e) 0.77, 90% interval 0.52 to 1.19. The upper end of that interval is the gene's LOEUF score, 1.19, which puts it in group 5 of 6, group 1 being the genes least tolerant of losing a copy. Missense variants: 193 observed, 228.75 expected, observed/expected ratio (o/e) 0.84, 90% interval 0.75 to 0.95. Synonymous variants: 80 observed, 81.05 expected, observed/expected ratio (o/e) 0.99, 90% interval 0.82 to 1.19.
Homologues: Orthologues: chimpanzee CD300LB (98% identical), macaque CD300LB (77% identical), pig CD300LB (61% identical), rat Cd300lb (58% identical), mouse Cd300lb (57% identical), guinea pig CD300LB (56% identical). Paralogues in human: CD300LF (48% identical), CD300LD (44% identical), CD300E (35% identical), CD300H (34% identical), CD300A (31% identical), CD300C (29% identical), FCMR (26% identical), CD300LG (25% identical), TREML1 (23% identical), TREM2 (22% identical), FCAMR (22% identical), PIGR (22% identical), and 1 more.
Diseases named in the same sentence as CD300LB in open-access papers:
CD300LB is named in the same sentence as 14 diseases in open-access papers, as found by Europe PMC text mining. Sharing a sentence is not in itself a finding about the gene and the disease. The quoted sentences say what the papers report.
glioma (1 paper, 2024). A benign or malignant brain and spinal cord tumor that arises from glial cells (astrocytes, oligodendrocytes, ependymal cells). "Interestingly, 2 of the most important features to distinguish oligodendroglioma, the gene FBX042 and the methylated gene CD300LB were also never reported in glioma studies." (PMID 38812741, 2024).
heart failure (1 paper, 2023). Inability of the heart to pump blood at an adequate rate to meet tissue metabolic requirements. "Additionally, high CD300LB expression in CD4+ T cells mediates the inflammatory response in patients with systemic lupus erythematosus and heart failure." (PMID 37152990, 2023).
male reproductive system diseases (1 paper, 2023). "Utilizing the CTD database, we demonstrated that the five hub genes (CD300LB, CMKLR1, CCR4, B3GALT5, and CTSK) significantly affected male reproductive system diseases." (PMID 37152990, 2023).
cancer (2 papers, 2023 to 2024). A tumor composed of atypical neoplastic, often pleomorphic cells that invade other tissues. "We found that CD300LB, CD300C, and CD300LF were significantly hypomethylated in almost all cancer types as compared to normal samples." (PMID 35642341, 2023).
renal diseases (1 paper, 2013). "So far, only the contribution of DAP12-associated myeloid receptors Cd300lb (commonly described as LMIR5) has been investigated in renal diseases showing that LMIR5 deficiency ameliorates mouse kidney IRI." (PMID 24358193, 2013).
CD300LB also shares sentences with these, for which no sentence is quoted: Sepsis (2 papers); Alzheimer disease (1); colitis (1); Crohn disease (1); hypothyroidism (1); oligodendroglioma (1); renal fibrosis (1); systemic lupus erythematosus (1); tumor (1).